IGFBP1 (insulin like growth factor binding protein 1)
Diseases named in the same sentence as IGFBP1 in open-access papers (continued):
Sharing a sentence is not in itself a finding about the gene and the disease.
diabetic ketoacidosis (1 paper, 2010). The metabolic condition resulted from uncontrolled diabetes mellitus, in which the shift of acid-base status of the body toward the acid side because of loss of base or retention of acids other than carbonic acid is accompanied by the accumulation of ketone bodies in body tissues and fluids. "In severe insulin deficiency, for example in diabetic ketoacidosis, IGFBP-1 is upregulated while hepatic IGF-1 secretion is reduced, despite increased GH." (PMID 20723227, 2010).
Ewing sarcoma (1 paper, 2022). A small round cell tumor that lacks morphologic, immunohistochemical, and electron microscopic evidence of neuroectodermal differentiation. "Data from the current study showed over-expression of IGF-1R, IGF-1, IGFBP-1, and 3 in local tumor tissues and serum of patients with Ewing sarcoma." (PMID 36713521, 2022).
glaucoma (1 paper, 2022). Increased pressure in the eyeball due to obstruction of the outflow of aqueous humor. "Based on two outstanding PE-associated pathways, including glaucoma and PE, identified by GSEA, ten key genes, including IGFBP1, CORIN, and C3, were revealed." (PMID 35647297, 2022).
glomerular disease (1 paper, 2021). "Others have also previously found that transgenic mice overexpressing human IGFBP-1 from the liver developed glomerular disease, suggesting persistent increases in systemic IGFBP-1 may be detrimental." (PMID 33758952, 2021).
growth failure (1 paper, 2008). "Higher mid-pregnancy levels of IGFBP-1 have been associated with growth failure." (PMID 18431506, 2008).
head and neck cancer (1 paper, 2010). A primary or metastatic malignant neoplasm affecting the head and neck. "One other study showed elevated levels of IGFBP1 (and IGFBP2) in plasma of patients with head and neck cancers." (PMID 20559444, 2010).
helminth infection (1 paper, 2020). "A lower level of insulin in helminth infection could lead to an increase in IGFBP-1 and -2 levels which eventually will result in a lower level of free IGF-131,32." (PMID 33149205, 2020).
hip fracture (1 paper, 2024). Traumatic or pathological injury to the hip in which the continuity of either the femoral head, femoral neck, intertrochanteric or subtrochanteric regions is broken. "Thus, the observed inverse association between meat intake and levels of IGFBP 1 and 2 and osteocalcin is consistent with our finding of a linear association between meat and hip fracture risk." (PMID 38632144, 2024).
HIV-1 infection (1 paper, 2019). The type species of lentivirus and the etiologic agent of acquired immunodeficiency syndrome (AIDS). "While a limitation of the study were the small number of cases, the study demonstrates that maternal HIV-1 infection might not have a dramatic influence on placental IGF1, IGFBP1, MMP2, MMP9, ANG1, ANG2 and Gal-13 levels in Cameroonian pregnant normotensive women with majority receiving cART." (PMID 31042729, 2019).
Hyperkeratosis (1 paper, 2018). Hyperkeratosis is a histopathological term defining a thickened stratum corneum and may be present in many different skin conditions, with many possible overlaps. "Reduced IGFBP-1 and IGFBP-2 levels could increase free IGF-1, thereby promoting the development of papillomatosis and hyperkeratosis observed in AN." (PMID 29706998, 2018).
hypothyroidism (1 paper, 2025). Abnormally low levels of thyroid hormone. "In the present study, assessment of these high‐affinity binding proteins revealed that hepatic expression of IGFBP1, ‐2, ‐3, and ‐4, and renal expression of IGFBP3 were all significantly impacted by fetal hypothyroidism at least two of the studied time points." (PMID 40693299, 2025).
IgA glomerulonephritis (1 paper, 2016). Inflammation of a specific segment of glomeruli within the kidney. "IGFBP-1 levels are also elevated in the kidneys in a mouse model of experimental IgA glomerulonephritis and in serum of patients with IgA glomerulonephritis." (PMID 27331812, 2016).
lung disease (1 paper, 2020). "IGFBP-1 and MMP-9 were selected to be associated with H3.1 containing cf-nucleosomes because of their correlation with lung disease." (PMID 32807242, 2020).
myopia (1 paper, 2023). "Further analysis using an insulin microarray resulted that the levels of insulin and those related factors including IGF2, IGF-2R, IGF binding protein 1 (IGFBP-1), IGFBP-2, IGFBP-3, IGFBP-4 and IGFBP-6 were markedly increased in patients with pathogenic myopia as compared with the controls." (PMID 38203671, 2023).
nephrotic syndrome (1 paper, 2021). A collection of symptoms that include severe edema, proteinuria, and hypoalbuminemia; it is indicative of renal dysfunction. "There is also evidence that IGFBP-1 may increase in nephrotic syndrome." (PMID 33758952, 2021).
non-alcoholic steatohepatitis (1 paper, 2024). "The up- or downregulation of additional genes that showed sex-specific responses (G0s2, Igfbp1, Mfsd2a, Myc, and Tat), as observed in the male rats, has been reported to increase lipid accumulation and lead to a non-alcoholic steatohepatitis-like phenotype." (PMID 38903859, 2024).
oral cancers (1 paper, 2017). "In our study, an increased serum level of IGFBP-1 was detected in patients with NPC, which is consistent with findings observed for oral cancer, which suggests that IGFBP-1 may play a cancer-promoting role in NPC rather than a tumour-suppressing role." (PMID 28143425, 2017). "In addition, serum levels of IGFBP-1 have been reported to be increased in metastatic prostate and oral cancers, but not in pancreatic, non-metastatic colorectal or endometrial cancers." (PMID 28143425, 2017).
ovarian disease (1 paper, 2025). "The Insulin-like Growth Factor Binding Protein 1 (IGFBP1) gene is associated with ovarian disease and HCC and influences gene expression and cellular responses to stimuli." (PMID 40699800, 2025).
ovarian endometriosis (1 paper, 2023). A non-neoplastic disorder characterized by the growth of endometrial tissue in the ovaries. "Specifically, the expression of KIR2DL4 was remarkably downregulated, while the expressions of PROK1, IGFBP1, RBP4, G2MB, KIR3DL1, and PRF1 were significantly upregulated in ovarian endometriosis." (PMID 37662927, 2023).
pancreatic (1 paper, 2020). "Recently, the overexpression of several let-7 downstream targets including HMGA2, IGFBP1, and IGFBP3, were found to define a distinct patient group with poor prognosis in pancreatic cancer." (PMID 32651364, 2020).
pulmonary arterial hypertension (1 paper, 2017). Pulmonary arterial hypertension (PAH) is a group of diseases characterized by mean pulmonary artery pressure >20 mmHg and elevated pulmonary arterial resistance leading to right heart failure. "The IGF-1 system is known to have a role in vascular pathologies, such as pulmonary arterial hypertension, and IGFBP-1 is one of a family of proteins modulating the effects of IGF-1 on vascular smooth muscle and endothelial cells." (PMID 28624389, 2017).
renal carcinoma (1 paper, 2023). A carcinoma arising from the epithelium of the renal parenchyma or the renal pelvis. "To explore to what extent the marked effects of PHT cell CM on HepG2 cell IGFBP-1 phosphorylation is specific to trophoblast cells, we examined the impact of CM collected from renal carcinoma cells in which RAPTOR or RICTOR was silenced." (PMID 37108437, 2023).
sarcopenia (1 paper, 2024). Progressive decline in muscle mass due to aging which results in decreased functional capacity of muscles. "Furthermore, our investigation revealed a positive correlation between appendicular lean mass in the extremities and IGFBP-1, indicating a potential association between sarcopenia and IGFBP-1 levels." (PMID 39507055, 2024). "The reverse study demonstrates a positive correlation between sarcopenia and IGF-1, as well as IGFBP-1." (PMID 39507055, 2024).
Thrombocytopenia (1 paper, 2022). A reduction in the number of circulating thrombocytes. "It was also shown that the inflammation-related cytokines IGFBP1 and RANTES diminished the megakaryocytic potential of hematopoietic stem cells after transplantation in patients with prolonged isolated thrombocytopenia." (PMID 35989938, 2022).
vaginal infection (1 paper, 2013). "For example, IGFBP1 has been considered as a marker for preterm in vaginal infection and leaking amniotic fluid." (PMID 23826308, 2013).
vitreous haemorrhage (1 paper, 2022). "Two proteins, namely IGFBP1 and PDGF-BB levels were significantly higher in the vitreous haemorrhage group." (PMID 36473885, 2022). "IGFBP1 and PDGF-BB were more related with vitreous haemorrhage than with macular traction/detachment." (PMID 36473885, 2022).
Zinc deficiency (1 paper, 2019). A deficiency of the essential metal Zinc; an essential cofactor for many enzymes. "Other experimental studies indicate that zinc deficiency decreased cell proliferation and related proteins such as hepatocyte growth factor (HGF), insulin like growth factor I (IGF), IGF binding protein 1 (IGFBP-1), MT, and cyclin D1, along with HNF-4α protein." (PMID 31174269, 2019).
tumor (106 papers, 1996 to 2026). "High IGFBP1 was associated with lower GC metastasis and inhibited the tumor cell migration and invasion owing to decreasing MMP9 expression in GC cells." (PMID 33931579, 2021). "This is reinforced by the observation that genes (Igfbp1 and Igfbp2) encoding insulin like growth factor binding proteins and insulin-induced gene 1 (Insig1) were downregulated in tumor of KO mice." (PMID 34685767, 2021). "And the expression of IGFBP1 is positively associated with tumor invasion, lymph node metastasis and vascular invasion." (PMID 32821544, 2020). "To further confirm this observation, we used western blot analyses to assess the expressions of ER, PR, FOXO1, a tumor suppressor located downstream of PR signaling, and insulin-like growth factor-binding protein 1 (IGFBP1), a factor associated with the decidua." (PMID 35717540, 2022). "Further studies uncovered that MMP9 and IGFBP1 were associated with tumor immune and progression." (PMID 33758602, 2021). "Intriguingly, IGFBP1 also seems to correlate with internal tumor burden, and thus may indicate increased risk for malignant transformation in patients with NF1." (PMID 23618374, 2013). "In line with this, these findings suggested that IGFBP1, which functions as a tumor suppressor, would be a possible target for treating HCC." (PMID 40699800, 2025). "Subsequent investigations revealed that IL-12A overexpression stimulated the expression of angiogenesis-associated proteins TIMP1, IGFBP1, and PAI1 in tumor cells." (PMID 39974277, 2025). "In contrast, CD276 and IGFBP1 were primarily expressed in epithelial cells, implying a potential engagement in modulating tumor biological behavior." (PMID 41488652, 2025). "Dual treatment targeting angiogenesis and IGFBP-1 significantly reduced tumor burden, and the mechanism was attributed to IGFBP-1/α5β1 integrin interactions in endothelial cells." (PMID 41226289, 2025). "In hepatocellular carcinoma tumors treated with anti-angiogenic therapy, hypoxia increases IGFBP-1 and promotes angiogenesis and tumor growth." (PMID 41226289, 2025). "In vivo experiments confirm that reduced IGFBP1 expression correlates with decreased metastasis and tumor growth, underscoring its significance in cancer progression and as a target for therapeutic intervention." (PMID 38700505, 2024). "Then, other pan-cancer analysis revealed that the expression of IGFBP1 in tumor tissues was significantly higher than that in normal tissues in TCGA-GBM, TCGA-LUAD, TCGA-COAD, TCGA-STES, TCGA-HMSC, and TCGA-THCA." (PMID 38700505, 2024). "Our findings also underscore the therapeutic potential of neutralization of tumor‐secreted IGFBP1 for the patients with metastatic lung cancer as well as the diagnostic potential of IGFBP1 levels in blood." (PMID 37296072, 2023). "Bioluminescence imaging of the mice showed that IGFBP1 depletion accelerated the diminishment of bioluminescence signals from tumor cells in lung tissues." (PMID 37296072, 2023). "Bioluminescence imaging of the mice showed that the depletion of IGFBP1 dramatically impaired lung metastasis of the cells, while restored expression of Flag‐rIGFBP1 almost completely rescued tumor metastasis of IGFBP1‐depleted cells." (PMID 37296072, 2023). "On the contrary, IGFBP1 overexpression slowed down the diminishment of tumor cell signals in lung and dramatically decreased the percentage of apoptotic cells in blood vessels of lung tissues." (PMID 37296072, 2023). "Taken together, these results demonstrate that secreted IGFBP1 is required for tumor cell migration and subsequent tumor metastasis." (PMID 37296072, 2023). "Collectively, these results indicate that IGFBP1 supports the survival of confined cells and enhances confined migration of tumor cells and therefore promotes tumor metastasis by inhibiting SOD2 S27 phosphorylation." (PMID 37296072, 2023).
tumor (continued). "In this study, the authors report that IGFBP1, a secreted protein, is upregulated in tumor cells during confined migration to promote metastasis." (PMID 37296072, 2023). "We next investigated the role of IGFBP1 in tumor metastasis in vivo by using lung metastasis mouse model via tail vein injection." (PMID 37296072, 2023). "Taken together, these results suggest that IGFBP1 promotes tumor metastasis by inhibiting cell apoptosis in blood vessels of lung tissues." (PMID 37296072, 2023). "Collectively, these results demonstrate that the expression and secretion of IGFBP1 were increased in tumor cells during confined migration at least partly in response to mechanical compression." (PMID 37296072, 2023). "Here it is shown that during spatially‐confined migration, the expression of insulin‐like growth factor‐binding protein 1 (IGFBP1) is upregulated in tumor cells." (PMID 37296072, 2023). "We adopted a compression device to apply mechanical force on cells and examined IGFBP1 expression in the cells subjected to mechanical compression, which showed that IGFBP1 expression is dramatically increased in tumor cells after compression." (PMID 37296072, 2023). "IGFBP1 promotes RCC tumor energy metabolism, including glucose uptake, lactate survival, and extracellular acidification rate, by recognizing the m6A modification site on LDHA mRNA and enhancing its mRNA stability, thereby accelerating tumor energy metabolism." (PMID 38117350, 2023). "Study has been confirmed that insulin-like growth factor-binding protein-1 (IGFBP-1) can mediate insulin sensitivity to provide tumor cells with the glucose needed for growth in tumor cells." (PMID 35903696, 2022). "IFN-γ, IGFBP-1, IL-23, Endoglin and Serpin E1 were elevated in tumor-bearing serum at both timepoints." (PMID 35962398, 2022). "Among them were genes associated with blood clotting (FGA, FGG) and genes associated with changes in the immune characteristics of a tumor (ENAM, IGFBP1, IL6)." (PMID 36028558, 2022). "To further study the functions of IGFBP1–7 in tumor progression, we analyzed their expression levels at different stages using TCGA data." (PMID 34745945, 2021). "GSEA was performed to discover potential molecular mechanisms of MMP9 and IGFBP1 in tumor immune and progression." (PMID 33758602, 2021). "After recruitment to the TME, TAMs release different factors—such as VEGF, IL-6, Angiopoietin 2 (ANG2), and insulin-like growth factor-binding protein 1 (IGFBP1)—to stimulate neovascularization in the tumor." (PMID 34503065, 2021). "Violin plots of IGFBP1–7 expression at different tumor stages showed an upward trend with increasing T stages." (PMID 34745945, 2021). "In the present study, IGFBP1 was identified as a regulator for tumor progression and immune in ccRCC." (PMID 33758602, 2021). "Cox multivariate regression analysis showed that besides tumor stages, IGFBP1 and IGFBP7 were independent predictors in STAD patients." (PMID 34745945, 2021). "The genes repressed in both GE1-HCC and GE2-HCC included those with supposed tumour-inhibiting activity, e.g. CXCL14, CCBE1, IGFBP1, RND3, BMP10 and COLEC10, which encode proteins involved in extracellular matrix remodelling, migration and the immune response." (PMID 33541355, 2021). "The evidence suggests that insulin stimulates tumor growth by decreasing the production of insulin-like growth factor-binding protein 1 (IGFBP-1), increasing the tissue bioavailability of Insuline-like growth factor (IGF)-I, or inhibiting apoptosis." (PMID 32340309, 2020). "Positive correlations between decreased expression of IGFBP1 and tumor differentiation, liver cirrhosis, microvascular invasion or metastasis, TNM stage and poor survival were found." (PMID 29702590, 2018). "IGFBP-1 protein was detected in all of the 16 NPC tumour tissues (100%) and in 3 of the 16 normal adjacent tissues (18.75%)." (PMID 28143425, 2017).